SERPINA1 (serpin family A member 1)
Diseases named in the same sentence as SERPINA1 in open-access papers (continued):
Sharing a sentence is not in itself a finding about the gene and the disease.
cystic fibrosis (67 papers, 2005 to 2025). Autosomal recessive disorder caused by pathogenic variants in the CFTR gene (cystic fibrosis transmembrane conductance regulator), which encodes a chloride and bicarbonate channel expressed in epithelial cells, and follow the diagnosis criteria. "SERPINA1 gene, encoding AAT protein, is known as a modifying gene of cystic fibrosis whereby our data allow speculating that AAT may facilitate CFTR-mediated epithelial fluid secretion and improve mucociliary clearance." (PMID 33946490, 2021). "Alpha 1-antitrypsin (A1AT/SERPINA1) deficiency and cystic fibrosis are important causes in western countries but how lower incidences in Asian populations." (PMID 30367658, 2018). "Several recessive Mendelian disorders are common in Europeans, including cystic fibrosis (CFTR), medium-chain-acyl-Co-A-dehydrogenase deficiency (ACADM), phenylketonuria (PAH) and alpha 1-antitrypsin deficiency (SERPINA1)." (PMID 26831755, 2016). "In literature there are reports on the combined carriership of CFTR and SERPINA1 gene variants in case of a clinical picture of cystic fibrosis, though without homozygous carriership of CFTR gene variant." (PMID 39881831, 2024). "For example, the balance between trypsin and alpha-1-antitrypsin (SERPINA1) is well-studied in the case of viral infection and cystic fibrosis where protease-inhibitor levels protect airways from an aberrant inflammatory response." (PMID 31462662, 2019).
lung carcinoma (49 papers, 2004 to 2025). "High expression of SERPINA1 in plasma is associated with poor prognosis and advanced clinical stage of lung cancer." (PMID 38710698, 2024). "In lung cancer patients, increased SerpinA1 expression was associated with metastasis and poor survival." (PMID 38279150, 2024). "It has also been demonstrated that IL-1β, an important inflammatory biomarker of COPD previously associated with lung cancer, is positively correlated with the SERPINA1 methylation levels." (PMID 36769181, 2023). "A recent study reported that, in male patients with COPD, higher levels of serum SERPINA1 methylation are associated with the development of lung cancer." (PMID 36769181, 2023). "In earlier reports related to lung cancer, SERPINA1 expression was found to promote the proliferation and migration of lung cancer." (PMID 38710698, 2024). "Recently, a growing body of research has confirmed that SERPINA1 shows a tremendous influence on multiple tumors, such as lung cancer, gastric cancer, and breast cancer." (PMID 37511325, 2023). "Previous studies have demonstrated that SERPINA1 was overexpressed in pancreatic and breast cancer tissues but downregulated in lung cancer." (PMID 37511325, 2023). "Increased SERPINA1 gene expression ameliorates tumour cell migration, apoptosis resistance, and colony formation, and SERPINA1 and its corresponding protein, AAT, influence the mechanisms of lung cancer." (PMID 34112123, 2021). "An increased bikunin on proteomic analysis seems to be related to recurrence of cancer, while SERPINA1 levels seem to decrease in the case of advanced lung cancer." (PMID 36046486, 2020). "According to our results, not only the uptake of exogenous AAT protein but also increased expression of SERPINA1 gene significantly enhances lung cancer cell migration, viability and resistance towards staurosporin-induced apoptosis." (PMID 31487965, 2019). "SerpinA1, a type of serine protease inhibitor, has been reported to modulate invasive and metastatic capacity in lung cancer, gastric cancer, and CRC." (PMID 26015410, 2015). "In non-small cell lung cancer, high expression of A1AT in plasma suggests that it is related to the poor prognosis of patients, and increased SERPINA1 in cell experiments has been shown to promote the proliferation and migration of lung cancer cells and inhibit apoptosis." (PMID 38710698, 2024). "Additionally, SerpinA1 has been shown to promote lung cancer metastasis through regulation of expression of FN." (PMID 38279150, 2024). "Additionally, upregulation of SerpinA1 has also been found to promote tumor migration and invasion in various cancer cell lines, including gastric, colon, breast, ovarian and lung cancer cells." (PMID 38279150, 2024). "However, little is known about glycosylation in PC although an increased level of serum fucosylated SERPINA1 has been reported in patients with lung cancer or hepatocellular carcinoma." (PMID 34199928, 2021). "We therefore sought to determine whether increased SERPINA1 expression and AAT protein levels affect lung cancer cell behavior in vitro." (PMID 31487965, 2019). "It is also of interest to clarify whether SERPINA1 gene and AAT protein play an active role in the pathogenesis of lung cancer or just reflect inflammatory reaction related to cancer development." (PMID 31487965, 2019). "In addition, serpinA1 is related to the distant metastasis of various cancers, including ovarian, cervical breast, and lung cancers." (PMID 26015410, 2015). "By blood proteomic analysis, researchers found that AMBP, α2 macroglobulin, and SERPINA1 might be valuable biomarkers for early detection of lung cancer using serum from 20 NSCLC and 10 healthy donors, and it would be better to perform a clinical validation in a larger cohort." (PMID 37475010, 2023).
lung carcinoma (continued). "Previous studies linking higher levels of serum AAT with a worse lung cancer prognosis, prompted us to analyze serum levels of AAT and to correlate them with SERPINA1 expression and AAT immunostainings in tumor and adjacent normal lung tissues." (PMID 31487965, 2019). "Our in vitro experiments clearly show that lung cancer cells highly differ in SERPINA1 expression levels and can uptake exogenous AAT protein." (PMID 31487965, 2019). "The detection of SERPINA1 transcripts in cultured lung cancer cells and the quantification of SERPINA1 expression in tumor and adjacent non-neoplastic lung tissue support the conclusion that cells in the lung express AAT protein itself." (PMID 31487965, 2019). "Our findings illustrate the significance of SERPINA1 expression and AAT protein levels in lung cancer, however, detail investigations on the mechanisms behind the regulation of SERPINA1 expression and AAT protein production in tumor cells are beyond the scope on this work." (PMID 31487965, 2019). "SERPINA1 gene and AAT protein play an active role in the pathogenesis of lung cancer and not just reflect inflammatory reaction related to cancer development." (PMID 31487965, 2019).
hepatocellular carcinoma (45 papers, 1984 to 2026). A malignant tumor that arises from hepatocytes. "Accumulation of the Z-variant AAT (the most frequent and severe mutation, encoded by SERPINA1*E342K) in the endoplasmic reticulum of liver cells has a gain of function proteotoxic effect on the liver, resulting in fibrosis, cirrhosis and/or hepatocellular carcinoma." (PMID 31817705, 2019). "Our aim was to compare the risk of hepatocellular carcinoma (HCC) in patients with liver cirrhosis carrying the SERPINA1 MM, MZ and MS genotypes." (PMID 34638908, 2021). "Our previous studies of SerpinA1 downregulation showed significantly increased TTR serum levels in HM30 mice, as well as in hepatoma cells." (PMID 34502397, 2021).
breast carcinoma (43 papers, 2004 to 2025). "A recent study found that SERPINA1 was a critical gene in breast cancer and periodontitis and was significantly associated with the prognosis of patients." (PMID 36072904, 2022). "In this study, we found that the hub genes CCNE1, PLK1, and SERPINA1 were significantly overexpressed, amplified, and mutated in breast cancer tissues compared with normal tissues." (PMID 36393842, 2022). "Higher levels of SERPINA1 has been associated with chemoresistance of human epithelial ovarian cancer and breast cancer and has also been proposed as a potential serum biomarker for GC." (PMID 31990955, 2020). "Moreover, in the context of breast cancer, current research has illuminated an association between reduced expression of SERPINA1 and more aggressive tumor phenotypes, poorer prognosis, and tumor metastasis." (PMID 38751445, 2024). "Conversely, other investigations have found that high SERPINA1 expression had a good prognosis in breast cancer based on TCGA gene expression data." (PMID 38424522, 2024). "In breast cancer, SERPINA1 was shown as a direct target gene of estrogen receptors and as a predictor of survival, but its splicing was not studied much." (PMID 38069324, 2023). "SERPINA1 is being used as an exploratory biomarker of breast cancer patient survival in a clinical trial of trastuzumab." (PMID 35887124, 2022). "Results showed that low expression of SERPINA1 predicts patients’ poor outcome, indicating SERPINA1 has anti-neoplastic roles in breast cancer." (PMID 36358879, 2022). "Our study showed that SERPINA1 is a potential protective gene expressed in breast cancer, which is consistent with previous studies." (PMID 34621293, 2021). "SERPINA1 is a suppressive gene in breast cancer and is the target gene directly regulated by PIWI-interacting small noncoding RNAs (piR-36026) and the response to molecular therapy." (PMID 34953500, 2021). "In the present study, we found low expression of SERPINA1 predicts patients’ poor outcome, indicating SERPINA1 functions anti-neoplastic roles in breast cancer." (PMID 34187256, 2021). "Of note, 14q LOH, which encompasses breast cancer genes such as SERPINA1 and DICER1, was highly enriched in HR−/HER2+ Nigerian women." (PMID 34836952, 2021). "Serpin peptidase inhibitor clade A member 1 (SERPINA1), a protease inhibitor, was reported to be a predictor in breast cancer and colorectal cancer." (PMID 32974202, 2020). "SERPINA1 was brought to our attention because it has been reported to be an ER-regulated gene in breast cancer cells." (PMID 26158350, 2015). "Currently there is no known predictive marker for the treatment outcome of ER+/HER2+ breast cancers, thus the ability of SERPINA1 to predict the survival of this intrinsic subtype of breast cancer patients is valuable." (PMID 26158350, 2015). "Although the results were not expected originally, we are excited about the potential predictive value of SERPINA1 transcript expression levels in the ER+/HER2+ breast cancer, since these patients have relatively poor prognosis." (PMID 26158350, 2015). "Based on our findings, we propose that the expression of SERPINA1, an ER and HER2 regulated gene, is linked to the outcome of ER+ and ER+/HER2+ breast cancer." (PMID 26158350, 2015). "Overexpression of SERPINA1 is linked to a poor prognosis in various tumors, including colorectal cancer, breast cancer and non-small cell lung cancer, but has not been described for ALL." (PMID 38350915, 2024). "This hints at a potential tumor-suppressive function of SERPINA1 in breast cancer, whereby its diminished expression may facilitate tumor progression and metastasis." (PMID 38751445, 2024). "However, it was paradoxical that SERPINA1 showed high expression in both breast cancer and liver metastasis, but predicted a better patient prognosis." (PMID 37180578, 2023).
breast carcinoma (continued). "Although SERPINA1 was overexpressed, amplified, and mutated, the difference in its expression between breast cancer and normal tissues was not significant." (PMID 36393842, 2022). "The differential expression of SERPINA1 has been associated with platinum resistance in human epithelial ovarian cancer, CDDP resistance in gastric cancer (GC), and tamoxifen resistance in breast cancer." (PMID 34737677, 2021). "Since ER is known to be activated through ER-HER2 crosstalk in ER+/HER2+ breast cancer cells, we performed experiments to determine whether the expression of SERPINA1 could be regulated by HER2." (PMID 26158350, 2015). "As indicated by a negative Cox score, a higher expression of SERPINA1 was found to associate with better patient survival outcome in the TCGA large patient cohort, and validated using the Curtis and Bild breast cancer patient cohorts." (PMID 26158350, 2015). "Since the majority of breast cancer patients are ER+, our finding that SERPINA1 can predict survival in ER+ patients suggests that it could be a potential prognostic marker, and many patients may benefit from this additional knowledge." (PMID 26158350, 2015). "Therefore, in ER+ breast cancers, the expression of SERPINA1 could be an indication of estrogen-mediated ER activation and its expression levels correlate to the survival." (PMID 26158350, 2015). "While the expression level of SERPINA1 was found to be higher in endocrine resistant cells than responsive cells, unexpectedly, the Kaplan Meier survival analysis revealed that high expression of this gene associated with better survival in ER and HER2 positive luminal B subtype of breast cancer." (PMID 26158350, 2015). "Serpin family A member 1 (SERPINA1) is a direct estrogen receptor target and a predictor of survival in breast cancer patients." (PMID 32525929, 2020). "Unexpectedly, our results allow us to hypothesize that the single gene SERPINA1 is a significant predictor of survival in ER+ and ER+/HER2+ breast cancer patients." (PMID 26158350, 2015). "SERPINA1 has been proposed as a biomarker for various diseases such as Cutaneous Squamous Cell Carcinoma, Hepatitis B, insulinomas, NSCLC, papillary thyroid carcinoma lung cancer and breast carcinoma." (PMID 26158350, 2015). "Among the identified transcripts, downregulation of COL6A2, SERPINA1, CCBE1, TFPI2, THBS1 and COL8A1 have been shown to promote migration and invasion of malign breast cancer cells, aggravate metastatic spread and result in poor prognosis of breast cancer patients." (PMID 31848385, 2019). "However, to date, no study has established a relationship between SERPINA1 and breast cancer." (PMID 39493752, 2024). "Furthermore, when SEPINA1 expression was divided into high and low by mean in this study, the KM survival analysis revealed no OS difference between the high and low SERPINA1 expression groups (p = 0.785), which was possible given the variable distributions of intrinsic types of breast cancer." (PMID 38424522, 2024). "Furthermore, although the splicing vector pSAD was initially developed to study the breast cancer genes BRCA1 and BRCA2, it has also been demonstrated to be a powerful tool to test other disease genes such as SERPINA1, CHD7, and UGT1A1, as well as others currently under investigation." (PMID 32211025, 2020).
diabetes (40 papers, 2011 to 2025). "For instance, a plasma serpin, Homo sapiens serpinA1, has been found to bind with proteins such as apolipoprotein and glucose-regulated proteins to maintain metabolic homeostasis, and a deficiency in serpinA1 can result in a series of metabolic diseases such as atheroma and diabetes mellitus." (PMID 38061001, 2023). "By correlation analysis in the current study, we found that SERPINA1 had the highest correlation coefficient not only for BCVA but also for the duration of diabetes." (PMID 38764026, 2024). "Our results showed that four isoforms of ITIH4 and one isoform of SERPINA1 (spots 669 and 683) had lower abundance in the diabetes remission group than in the non-diabetic group and an intermediate value in the persistent diabetes group." (PMID 34501327, 2021). "Among them, SERPINA1, A2M, and AGT fluctuations are known to be associated with embryogenesis and pregnancy condition and long-term diabetes mellitus." (PMID 33184417, 2020). "Notably, SERPINA1 displayed the highest correlation coefficient not only for BCVA but also for the duration of diabetes." (PMID 38764026, 2024). "Interestingly, SERPINA1 had the highest correlation coefficient not only for BCVA (r = -0.643) but also for the duration of diabetes (r = 0.679)." (PMID 38764026, 2024). "In addition, in order to exclude diabetes as a confounding factor, a correlation between diabetes and SERPINA1 promoter methylation was assessed." (PMID 33858475, 2021). "SERPINA1 was associated with metabolic networks 1 and 2 (top metabolites: total cholesterol in IDL and mean diameter of VLDL, respectively), which are mainly related to cholesterol and triglyceride pathways of apoB-containing lipoproteins as well as diabetes associated amino acids." (PMID 22916037, 2012). "We further discovered marked changes in prediabetes/diabetes-related proteins (AACT/SERPINA3, AAT/SERPINA1, ApoA-I, HP, RBP4, TTR, and ZAG)." (PMID 31504048, 2019). "SERPINA1 was the protein with the highest correlation coefficient not only for BCVA but also for the duration of diabetes." (PMID 38764026, 2024). "The whole pool of ACS patients (n = 115) was stratified in patients with (n = 28) and without (n = 87) diabetes, and SERPINA1 hypermethylation rates were compared." (PMID 33858475, 2021). "SERPINA1 was hypermethylated in 100% (9/9) of COPD+ patients with diabetes and in 71.4% (15/21) of COPD+ patients without diabetes (p > 0.05)." (PMID 33858475, 2021). "A total of 67.9% (19/28) and 60.9% (53/87) of ACS patients with and without diabetes, respectively, presented SERPINA1 hypermethylation (p > 0.05)." (PMID 33858475, 2021). "Moreover, 52.6% (10/19) and 57.6% (38/66) of COPD− patients with and without diabetes, respectively, presented SERPINA1 hypermethylation (p > 0.05)." (PMID 33858475, 2021). "Regarding differences among the non-diabetic, diabetes remission, and persistent diabetes groups, considering the samples obtained before and after surgery as a whole, we found different abundances in nine spots from five proteins: CP, SERPINA1, ITIH4, plasminogen (PLG), and FGG." (PMID 34501327, 2021). "ACS patients were afterward stratified according to diabetes status in COPD+ with (n = 9) and without diabetes (n = 21) as well as in COPD− with (n = 19) and without diabetes (n = 66), and SERPINA1 hypermethylation rates were compared." (PMID 33858475, 2021).